TMEM177 (transmembrane protein 177)
Description:
Plays a role in the early steps of cytochrome c oxidase subunit II (MT-CO2/COX2) maturation and is required for the stabilization of COX20 and the newly synthesized MT-CO2/COX2 protein.
Synonyms: MGC10993
Tractability: Antibody: UniProt predicts a signal peptide or a membrane-spanning region. PROTAC: its protein half-life has been measured.
Gene: Protein-coding gene on chromosome 2 (119,679,137 to 119,686,507, forward strand). Ensembl gene ENSG00000144120.
Subcellular location: Mitochondrion inner membrane
Pathways (Reactome):
Metabolism: Complex IV assembly
Gene Ontology:
Molecular function: protein binding
Cellular component: mitochondrial inner membrane; mitochondrion; membrane
Genetic constraint (gnomAD): Loss-of-function variants: 8 observed, 17.8 expected, observed/expected ratio (o/e) 0.45, 90% interval 0.26 to 0.81. The upper end of that interval is the gene's LOEUF score, 0.81, which puts it in group 3 of 6, group 1 being the genes least tolerant of losing a copy. Missense variants: 336 observed, 415.75 expected, observed/expected ratio (o/e) 0.81, 90% interval 0.74 to 0.88. Synonymous variants: 173 observed, 178.17 expected, observed/expected ratio (o/e) 0.97, 90% interval 0.86 to 1.1.
Homologues: Orthologues: macaque TMEM177 (91% identical), rabbit TMEM177 (81% identical), guinea pig TMEM177 (79% identical), pig TMEM177 (79% identical), rat Tmem177 (79% identical), mouse Tmem177 (78% identical), tropical clawed frog tmem177 (44% identical), zebrafish tmem177 (41% identical), Drosophila melanogaster CG33506 (23% identical), Caenorhabditis elegans R144.12 (19% identical), Caenorhabditis elegans R144.11 (18% identical).
Diseases named in the same sentence as TMEM177 in open-access papers:
TMEM177 is named in the same sentence as 2 diseases in open-access papers, as found by Europe PMC text mining. Sharing a sentence is not in itself a finding about the gene and the disease. The quoted sentences say what the papers report.
cancer (1 paper, 2026). A tumor composed of atypical neoplastic, often pleomorphic cells that invade other tissues. "Knockdown of RPS2 or TMEM177 in CRC cells resulted in anti-cancer effects and disruption of MMP and OXPHOS." (PMID 41597199, 2026).
TMEM177 also shares sentences with these, for which no sentence is quoted: tumor (1 paper).